DNMT3A (DNA methyltransferase 3 alpha)
Diseases named in the same sentence as DNMT3A in open-access papers (continued):
Sharing a sentence is not in itself a finding about the gene and the disease.
Cognitive impairment (10 papers, 2015 to 2024). Abnormal cognition is characterized by deficits in thinking, reasoning, or remembering. "The loss of Dnmt1 and Dnmt3a in the adult brain leads to cognitive deficits in mice; and mutant Tet1 animal exhibits abnormal hippocampal long-term depression and impaired memory extinction." (PMID 26015403, 2015). "For example, decreased H3K9 methylation in the hippocampus have been found in aged rats; BDNF, cFOS, and deoxyribonucleic-acid-methyltransferase-3a (DNMT3A), all of which were associated with cognitive impairment during the aging process, also undergo expression alterations." (PMID 33192481, 2020). "Recently, a report states that transient over-expression of Dnmt3a2, a Dnmt3a isoform, in mouse hippocampus can restore age-associated cognitive deficits and inhibition of hippocampal Dnmt3a2 expression by shRNAi leads to a damage in young mouse cognitive behavioral." (PMID 26015403, 2015). "It was found that the up-regulation of miR-29c prevented cognitive impairment in 5xFAD mice, possibly by inhibiting the expressions of DNMT3A, DNMT3B, and BACE1 in the hippocampus." (PMID 34750393, 2021). "In contrast, both overexpressing DNMT3a or knockdown LRG1 in hippocampus can attenuate the synaptic disorders and rescue postoperative cognitive deficits in aged mice." (PMID 39722450, 2024).
Intellectual disability (10 papers, 2017 to 2025). "As the first reported case from Saudi Arabia to our knowledge, it broadens the clinical and geographic spectrum of the disorder and highlights the association between DNMT3A variants, intellectual disability, and ASD." (PMID 41384217, 2025). "For instance, germline mutation in DNMT3A led to Tatton-Brown-Rahman syndrome, with some patients suffering from mild to severe intellectual disability." (PMID 39678047, 2024). "Mutations in DNMT3A are closely associated with neurodevelopmental disorders, such as autism spectrum disorder and intellectual disabilities, further highlighting its essential role in maintaining neural health during differentiation." (PMID 39678047, 2024). "Mutations in DNMT1 are associated with neuropathies, mutations in DNMT3A cause overgrowth syndromes with intellectual disability, and DNMT3B mutations are involved in immunodeficiency and intellectual disability." (PMID 35997367, 2022). "Another gene of which heterozygous loss of function is associated with tall stature and intellectual disability is DNA methyltransferase 3A (DNMT3A), while gain of function of DNMT3A leads to dwarfism." (PMID 34194391, 2021). "We report a Japanese patient with severe intellectual disability and autism spectrum disorder with a de novo mutation in the active domain of DNMT3A." (PMID 32435502, 2020). "TBRS constitutes a rare syndrome characterized by overgrowth and intellectual disability (OGID), predominantly resulting from de novo heterozygous mutations in the DNMT3A gene." (PMID 41384217, 2025).
multiple myeloma (10 papers, 2019 to 2025). "In myeloma patients, DNMT3A mutations were present with a VAF range of 2–19%, and TET2 mutations with a VAF range of 14% to 54%." (PMID 40869343, 2025). "Among 60 patients (multiple myeloma, n = 51; non-Hodgkin lymphoma, n = 6; Hodgkin lymphoma, n = 3), CH-associated mutations were identified in 53% pre-ASCT, predominantly involving DNMT3A." (PMID 41419602, 2025). "Because piRNA-823 is directly related to DNA methyltransferase 3A (DNMT3A) and 3B (DNMT3B) in myeloma cells, piRNA-823 inhibition using a piRNA-823 antagomir (antagomir-823) was shown to result in significant decreases in DNMT3A and DNMT3B expression." (PMID 34199285, 2021). "In multiple myeloma, piRNA‐823 exhibits a positive correlation with Dnmt3a/3b, directly participating in regulating the aberrant DNA methylation of gene promoter regions to inactivate putative tumour‐suppressor genes." (PMID 32227582, 2020). "The most common emergent mutation was in DNMT3A, found in five of the 10 new CH cases, suggesting that standard multiple myeloma therapy does not promote CH mutations different from those seen in the general population." (PMID 38019104, 2023). "Multiple myeloma therapy, which primarily included IMiDs, proteasome inhibitors, and ASCT, led to a significant increase in CH prevalence that was mainly driven by DNMT3A clonal expansion." (PMID 38019104, 2023).
peripheral T-cell lymphoma (10 papers, 2016 to 2025). "Here we show that 12% of Dnmt3a-deficient mice develop CD8+ mature peripheral T cell lymphomas (PTCL) and 29% of mice are affected by both diseases." (PMID 27690235, 2016). "Here we show that Dnmt3a is a haploinsufficient tumor suppressor in the prevention of peripheral T cell lymphomas in mice." (PMID 27690235, 2016). "In tumors, inactivation of DNMT3A has also been linked to the development of peripheral T cell lymphoma (PTCL) and lung tumors, suggesting that DNMT3A may act as TSGs." (PMID 39996888, 2025). "Moreover, DNMT3A inactivation leads to the progression of peripheral T cell lymphoma (PTCL) and lung tumors, thus indicating that DNMT3A may act as a tumor-suppressor gene." (PMID 28127428, 2017). "In this study we show that loss of Dnmt3a in HSPCs in EμSRα-tTA;Teto-Cre;Dnmt3afl/fl; Rosa26LOXPEGFP/EGFP mice not only results in the development of CLL but also in the development of peripheral T cell lymphomas in ~40% of Dnmt3aΔ/Δ mice either alone or in combination with CLL." (PMID 27690235, 2016). "We have previously reported that Dnmt3a inactivation in hematopoietic stem cells results in chronic lymphocytic leukemia (CLL) and CD8-positive peripheral T cell lymphomas (PTCL) in EμSRα-tTA;Teto-Cre;Dnmt3afl/fl; Rosa26LOXPEGFP/EGFP (Dnmt3aΔ/Δ) mice." (PMID 27677595, 2016). "In addition, we previously reported that combined inactivation of Dnmt3a and Dnmt3b results in the development of CLL and peripheral T cell lymphoma (PTCL), however the molecular basis of PTCL is poorly understood." (PMID 27690235, 2016). "Additionally, studies on cytotoxic peripheral T-cell lymphoma, not specifically focused on EBV+ cases, revealed frequent mutations in epigenetic modifiers, such as TET2, DNMT3A, and genes involved in the JAK/STAT pathway." (PMID 38921179, 2024).
Stroke (10 papers, 2013 to 2025). Sudden impairment of blood flow to a part of the brain due to occlusion or rupture of an artery to the brain. "Recent studies have found that the presence of CHIP mutations, specifically DNMT3A, is significantly associated with stroke and its severity." (PMID 40287867, 2025). "This is similar to our results to a certain extent, indicating a possible association between DNMT3A functional deficits via inflammation and poor functional outcomes after stroke." (PMID 39006763, 2024). "Similarly, mutation in another epigenetic regulator, DNMT3A, was associated with functional disability, after adjusting for initial stroke severity, the use of intravenous thrombolysis or mechanical thrombectomy, and occurrence of hemorrhagic transformation." (PMID 40093911, 2025). "Our results can be validated in another cohort research, which reported that DNMT3A‐CHIP is significantly linked to worse initial stroke severity as measured by the NIHSS score and a higher risk of hemorrhagic transformation and functional disability at 90 days poststroke." (PMID 39006763, 2024). "Our study suggests that somatic mutations in DNMT3A are significantly associated with poor short‐term neurological functional outcomes after stroke, especially in the subgroup of patients with higher hsCRP or IL‐6 levels at baseline and mRS scores at discharge." (PMID 39006763, 2024). "However, we recently reported that the presence of DNMT3A‐driven CHIP increases the risk of short‐term recurrent stroke in first‐ever AIS patients." (PMID 39006763, 2024). "These mutations, notably in genes like DNMT3A, TET2, and JAK2, induce pro-inflammatory and pro-atherosclerotic processes, promoting vascular damage and stroke risk." (PMID 39997650, 2025). "As DNMT3A‐CHIP is a pre‐existing condition in stroke patients, we administered the inhibitor once daily for 3 days prior to surgery and again at reperfusion onset to better simulate this clinical context." (PMID 39006763, 2024). "With a stroke mouse model of transient middle cerebral artery occlusion (tMCAO), we demonstrated that DNMT3A protein levels in the brain penumbra increased." (PMID 39006763, 2024). "It reveals that DNMT3A inhibition can offer central neuroprotection, while peripheral DNMT3A inhibition increases inflammation and stroke severity." (PMID 39006763, 2024). "Notably, we found that when DNMT3A function was inhibited, RNA‐seq results showed that most genes in the ischemic penumbra of stroke were upregulated, which is consistent with previous studies." (PMID 39006763, 2024). "We found that DNMT3A inhibition by RG108 in a tMCAO stroke mouse model increased infarct volume and exacerbated neurobehavioral function, which is inconsistent with previous reports that inhibition of DNMTs function with antagonists or siRNA exerts neuroprotective effects." (PMID 39006763, 2024). "Similarly, hypomethylation of TNF receptor-associated factor 3 (TRAF3), hypermethylation of thrombospondin-1 (THBS1), and increased DNA methyltransferase 3A (DNMT3A) activity are indicated as predictors of stroke outcome." (PMID 36855111, 2023). "Similarly, hypomethylation of TNF receptor-associated factor 3 (TRAF3), hypermethylation of thrombospondin-1 (THBS1), and increased DNMT3A activity are indicated as predictors of stroke outcome, as well degree of ischemic injury." (PMID 36855111, 2023). "Bioinformatic analysis revealed DNA (cytosine-5)-methyltransferase 3a (DNMT3a) as a target of miR-29c, suggesting that increased DNMT3a expression in ischemic brain may contribute to stroke injury." (PMID 25821444, 2015). "Therefore, we illustrated that dysfunction of DNMT3A leads to the increase and infiltration of peripheral and central neutrophils and the excessive activation of proinflammatory processes, which in turn leads to a worse functional prognosis after stroke." (PMID 39006763, 2024).
Stroke (continued). "The levels of DNMT3a, DNMT3b, and DNMT1 in the contralesional cortex after a stroke (p < 0.001, n = 6) significantly increased." (PMID 29997355, 2018).
thymoma (10 papers, 2014 to 2025). A neoplasm arising from the epithelial cells of the thymus. "A functional role of this gene in thymic epithelial tumors emerged from studies that focused on mutation analysis, revealing that DNMT3A is one the most frequently mutated genes in thymic carcinoma, and that the mutation p.G728D is associated with B3 thymomas." (PMID 27999265, 2016). "From the DNA promoter methylation analyses performed in this study, the involvement of MTHFR and DNMT3A methylation in thymoma-associated myasthenia gravis has been proven, even if other studies are needed to assess a potential pathogenic role of these genes in TAMG." (PMID 27999265, 2016). "The most frequently mutated genes within each subtype were as follows: PCLO (27%), POT1 (27%), and STAT3 (27%) in idiopathic PRCA; STAT3 (20%), DNMT3A (10%), and CUX1 (10%) in thymoma-associated PRCA; and STAT3 (54%) and TET2 (12%) in LGLL-associated PRCA." (PMID 40202536, 2025). "Compared to early-stage TET, there was a decrease in global DNA methylation levels, while the expression of DNMT1, DNMT3a, and DNMT3b increased in advanced-stage thymomas." (PMID 38338833, 2024). "In comparison with early-stage TEN, global DNA methylation levels were found to be reduced, whereas DNMT1, DNMT3a, and DNMT3b expression was increased in advanced-stage thymomas." (PMID 35409405, 2022). "In conclusion, the present study revealed increased MTHFR promoter methylation in thymomas obtained from MG patients and some degrees of methylation of the DNMT3A gene in thymic tissue with respect to blood were observed." (PMID 27999265, 2016). "The present study suggests that MTHFR methylation is increased in thymomas obtained from MG patients; furthermore, some degrees of methylation of the DNMT3A gene were observed in thymic tissue with respect to blood." (PMID 27999265, 2016). "In this article, we report the identification of DNMT3A and ASXL1 mutations in a cytogenetically normal stage IVB type B3 thymoma." (PMID 25000259, 2014). "The extent of DNMT3A and ASXL1 mutations in thymoma should be explored, and treatments targeting epigenetic reprogramming should be considered in the future." (PMID 25000259, 2014). "Our results show that mutations in DNMT3A and ASXL1 have a role in the development of thymoma." (PMID 25000259, 2014). "Genes involved in histone modification (BAP1, 13%; SETD2, 11%; ASXL1, 4%), chromatin remodelling (SMARCA4, 4%), and DNA methylation (DNMT3A, 7%; TET2, 4%; WT1, 4%) were frequently mutated in thymic carcinomas, but not thymomas." (PMID 35884448, 2022). "In a recent study, nine out of thirty nine mutated genes (23%) were involved in epigenetic regulation, with 34% of TCs exhibiting recurrent mutations in seven of them (BAP1, ASXL1, SETD2, SMARCA4, DNMT3A, TET2, and WT1), an observation which was not present for thymomas." (PMID 38338833, 2024).
triple-negative breast carcinoma (10 papers, 2018 to 2024). An invasive breast carcinoma which is negative for expression of estrogen receptor (ER), progesterone receptor (PR), and human epidermal growth factor receptor 2 (HER2). "Not only that, we also found that the regulatory axis of DNMT3A/3B-TAT is applicable in triple-negative breast cancer (TNBC)." (PMID 39334853, 2024). "For instance, MYC and DNMT3A-mediated DNA methylations on the miR-200b promoter repress triple negative breast cancer migration, invasion, and cancer stem cell-like properties." (PMID 35860691, 2022). "The expression levels of DNMT1 and DNMT3A showed highest expression levels in triple negative breast cancer patients, where previous studies have observed hypermethylation of tumor suppressor genes." (PMID 33604794, 2021). "Previously, a study report has decoded that MYC interacts with DNMT3a, thus silencing miR-200b and leading to EMT in triple-negative breast cancer." (PMID 34623601, 2022). "In Triple Negative Breast Cancer, coupled with MYC, DNMT3a promotes the epithelial to mesenchymal transition and mammosphere formation of TNBC cells by upregulating miR-200b promoter methylation." (PMID 33234142, 2020). "In triple-negative breast cancer cells, binding of MYC to the miR-200b/200a/429 promoter leads to recruitment of DNMT3A to promoter CpGs, resulting in promoter methylation; negative feedback control is provided by direct targeting of the DNMT3A mRNA by miR-200b." (PMID 34884985, 2021).
lung adenocarcinoma (9 papers, 2021 to 2026). A carcinoma that arises from the lung and is characterized by the presence of malignant glandular epithelial cells. "Therefore, it was demonstrated that the downexpression of DNMT3A in lung adenocarcinoma might be together with a poor prognosis." (PMID 36091786, 2022). "However, the role and mechanism of DNMT3a in lung adenocarcinoma (LUAD) remain unknown." (PMID 39990668, 2025). "However, in lung adenocarcinoma (LUAD), the relationship between the expression level of DNMT3a and clinical prognosis remains to be explored, and the molecular mechanism by which DNMT3a mediates malignant tumour progression remains unclear." (PMID 39990668, 2025). "In lung adenocarcinoma, DNMT3A/3B had a negative correlation with PLK3." (PMID 34080290, 2021).
Alzheimer disease (8 papers, 2017 to 2024). A progressive, neurodegenerative disease characterized by loss of function and death of nerve cells in several areas of the brain leading to loss of cognitive function such as memory and language. "Developmental Pb exposure not only altered DNA methylation in both specific gene level and global genome level in brain of Alzheimer’s disease model, but also could affect the expression of DNA methyltransferase 1(DNMT1) and DNA methyltransferase 3a (DNMT3a) in hippocampus." (PMID 28107465, 2017). "Given the heterogeneity of this group of patients, we analyzed the differences in DNMT3a expression between different types of Dementia and did not observe significant differences in DNMT3a expression between Senile Dementia, Mixed Dementia, Alzheimer disease or Vascular Dementia." (PMID 32210102, 2020).
angioimmunoblastic T-cell lymphoma (8 papers, 2017 to 2025). A mature T-cell non-Hodgkin lymphoma, characterized by systemic disease and a polymorphous infiltrate involving lymph nodes and extranodal sites. "For example, DNMT3A is overexpressed in 30% of angioimmunoblastic T-cell lymphoma (AITL) and 40% of DLBCL and is associated with reduced overall survival (OS) and event-free survival (EFS) in DLBCL patients." (PMID 35463343, 2022). "PTCL-TBX21 appear to show mutations in genes regulating DNA methylation, such as in TET1, TET3, and DNMT3A, however, are still less frequent in this subgroup than in angioimmunoblastic T-Cell lymphoma." (PMID 35330161, 2022). "Beginning with nodal PTCLs, up to 60–100% of angioimmunoblastic T-cell lymphoma (AITL) and up to 40% of PTCL not otherwise specified (PTCL-NOS) demonstrate surface markers of follicular helper T (TFH) cells and have common genetic features, such asRHOA,TET2,DNMT3A, andIDH8–11." (PMID 29259783, 2017).
bladder cancer (8 papers, 2020 to 2025). "5-azacytidine inhibits cell proliferation by reversing the abnormally high methylation of the hepaCAM gene through the downregulation of DNMT3A/3B expression in bladder cancer cells." (PMID 39304654, 2024). "Our study, to our knowledge, represents the first attempt to examine the role of DNMT3A in bladder cancer stemness and invasion." (PMID 36077697, 2022). "Having demonstrated the effects of the SNHG1/DNMT3A/miR-129-2-5p/Rac1 effector pathway on promoting bladder cancer cell stemness and invasion, we investigated more directly the functional relationship between stemness and invasion." (PMID 36077697, 2022). "MYC is upregulated in bladder cancer, which represses miR-29 expression, leading to increased levels of the target DNA methyltransferase 3 alpha (DNMT3A)." (PMID 36497229, 2022). "By defining a functional signaling pathway, i.e., SNHG1/DNMT3A/miR-129-2-5p/Rac1, that drives stemness and invasion in advanced bladder cancer cells, our study should spur additional investigation into the value of therapeutically targeting components of this pathway." (PMID 36077697, 2022). "Overall, we believe that the identification of the SNHG1/DNMT3A/miR-129-2-5p/Rac1 effector pathway that plays a major role in driving bladder cancer stemness and invasion may help develop a new therapeutic approach to treat this difficult disease." (PMID 36077697, 2022). "However, the expression status of DNMT3A in different bladder cancer variants has not been carefully assessed." (PMID 36077697, 2022). "Our data strongly suggest that the SNHG1/DNMT3A/miR-129-2-5p/Rac1 effector pathway drives stem-cell-like and invasive behaviors in MIBC, a deadly form of bladder cancer." (PMID 36077697, 2022). "By identifying the DNMT3A/miR-129-2-5p/Rac1 signaling pathway downstream of SNHG1 that is operative in advanced bladder cancer cells, we are in no way ruling out other potential pathways or components that might also mediate the activities of SNHG1." (PMID 36077697, 2022).